TRAF6 (TNF receptor associated factor 6)
Diseases named in the same sentence as TRAF6 in open-access papers (continued):
Sharing a sentence is not in itself a finding about the gene and the disease.
intracerebral hemorrhage (3 papers, 2021 to 2022). A cerebrovascular disorder characterized by bleeding into one or both cerebral hemispheres including the basal ganglia and the cerebral cortex. "Zinc finger protein A20 suppressed the inflammatory response following intracerebral hemorrhage by regulating TRAF6 polyubiquitination." (PMID 33967693, 2021). "Neuroinflammation was alleviated by blocking of the TRAF6/NLRP3 interaction during intracerebral hemorrhage that may shed new light on intracerebral hemorrhage treatment in clinic." (PMID 33967693, 2021). "Similarly, it has been reported that A20 reduces inflammation by regulating TRAF6 polyubiquitination after intracerebral hemorrhage." (PMID 34381441, 2021).
metabolic syndrome (3 papers, 2010 to 2023). A cluster of metabolic risk factors for CARDIOVASCULAR DISEASES and TYPE 2 DIABETES MELLITUS. "However, TRAF6 also interacts with proteins known to attenuate atherosclerotic lesion formation: recently it could be shown, that TLR5- deficient mice develop a metabolic syndrome." (PMID 20644648, 2010).
Myocardial fibrosis (3 papers, 2018 to 2025). "Improved cardiac function and reduced myocardial fibrosis are noted in animals treated with cardiosphere-derived cell-secreted exosomes depending on miR-146a-5p decreases the expression of TRAF6, Smad4, and FOS." (PMID 40492132, 2025). "In myocardial fibrosis, has-circ-0000672 can act as a ceRNA, targeting miR-516a-5p and decreasing its expression, resulting in decreased binding of miR-516a-5p to its target gene, TRAF6 mRNA 3'-UTR, and facilitating the development of myocardial fibrosis." (PMID 39113708, 2024). "Ang II infusion significantly increased myocardial fibrosis, expression of collagen I, collagen III, and TGF-β1, as well as TGF-β1 downstream proteins p-Smad2, p-Smad3, TRAF6, and p-TAK1 (all p<0.05)." (PMID 30175152, 2018).
non-alcoholic fatty liver disease (3 papers, 2019 to 2024). "LILRB4 inhibits the expression of TRAF6 and downstream inflammatory factors, thereby inhibiting the occurrence and development of non-alcoholic fatty liver disease." (PMID 31138763, 2019). "OTUB1 also inhibits the polyubiquitination of TRAF6 and the subsequent activation of the ASK1 signaling pathway, playing a critical protective role in non-alcoholic fatty liver disease." (PMID 39500879, 2024).
pancreatitis (3 papers, 2015 to 2025). Inflammation of the pancreas. "Overall, our data suggest that miR‐146a regulates the inflammation of experimental pancreatitis by inactivating transcription factors and the TRAF6–NF‐κB signaling pathway, which attenuates the release of proinflammatory cytokines." (PMID 40018991, 2025). "In the current study, we revealed for the first time that Traf6 functioned as an adaptor in the progression of mild pancreatitis into severe pancreatitis through degradation of Traf6 protein." (PMID 26633718, 2015). "Since uncontrolled inflammatory responses are central to the deterioration of AP, causing enormous burdens and increased morbidity for patients, our results showed that Traf6 is a key modulator in pancreatitis progress and a promising biochemical target for the treatment of AP." (PMID 26633718, 2015). "This may explain why in the mice with acute necrosis pancreatitis, which was induced by the combination treatment of caerulein and LPS, the Traf6 level was lower compared with those in the AEP." (PMID 26633718, 2015).
renal fibrosis (3 papers, 2024 to 2025). A final common manifestation of a wide variety of chronic kidney diseases characterized by glomerulosclerosis and tubulointerstitial fibrosis. "The progression of renal fibrosis in LN is closely linked with the miR-146a-TRAF6 axis." (PMID 39104393, 2024). "For example, TRAF6 mediates KLF5 K63-linked ubiquitination, promoting nuclear localization and enhancing gene activation, contributing to renal fibrosis regulation." (PMID 38735939, 2024). "Inhibits EMT and inflammation, reducing renal fibrosis by targeting TRAF6 and IRAK1." (PMID 40895189, 2025).
severe combined immunodeficiency (3 papers, 2019 to 2023). Severe combined immunodeficiency (SCID) comprises a group of rare monogenic primary immunodeficiency disorders characterized by a lack of functional peripheral T lymphocytes resulting in early-onset severe respiratory infections and failure to thrive. "Severe combined immunodeficiency (SCID) is causedby a large deletion on chromosome 11 spanning the RAG1and RAG2 genes and the 5′-region of TRAF6 (Weisz Hubshmanet al., 2017)." (PMID 37465191, 2023).
Splenomegaly (3 papers, 2022 to 2025). Abnormal increased size of the spleen. "The TRAF6[L74H] mice displayed splenomegaly with an increase in spleen weight and spleen cell number." (PMID 35157702, 2022). "ROSAH (retinal dystrophy, optic nerve edema, splenomegaly, anhidrosis, and headache) syndrome is a rare genetic disease caused by variants in alpha-kinase 1 (ALPK1) resulting in downstream pro-inflammatory signaling mediated by the TIFA/TRAF6/NF-κB pathway." (PMID 40925900, 2025).
triple-negative breast carcinoma (3 papers, 2022 to 2025). An invasive breast carcinoma which is negative for expression of estrogen receptor (ER), progesterone receptor (PR), and human epidermal growth factor receptor 2 (HER2). "TRAF6 depletion induces decitabine resistance in triple-negative breast cancer by blocking decitabine-induced DNA methyltransferase DEGs radiation." (PMID 36163484, 2022).
ulcerative colitis (3 papers, 2019 to 2023). An inflammatory bowel disease involving the mucosal surface of the large intestine and rectum. "Decreases IL-1β, TNF-α, MDA, MPO, NF-κB p65, TRAF6, LC3, Beclin1, p62 levels and cell apoptosis; increases SOD activity; and exerts obvious therapeutic effect on rat ulcerative colitis." (PMID 35566359, 2022). "Moreover, tRXRα expressed in ulcerative colitis patients could interact with TRAF6." (PMID 30931933, 2019).
abortion (2 papers, 2021 to 2025). the ending of pregnancy by removing a fetus or embryo before it can survive outside the uterus. "In addition, M1 macrophages can suppress trophoblast invasion and migration, leading to recurrent spontaneous abortion, which occurs indirectly by inhibiting TRAF6 expression at the mRNA level in mice." (PMID 40218311, 2025).
allergies (2 papers, 2013 to 2022). "This study provides a possibility that the improvement effect of SD treatment on allergies and inflammation in AR mice may be related to the TLR4/TRAF6/NF-κB and IL-6/ROR-γt/STAT3 pathways and intestinal microflora modulation." (PMID 36276863, 2022).
brain hemorrhage (2 papers, 2021 to 2023). "The polyphenolic flavone Luteolin has shown the capacity to inhibit microglia activation by reducing the release of inflammatory mediators and alleviate neuroinflammation induced in an in vivo brain hemorrhage model by downregulating TLR-4/TNF receptor-associated factor 6 (TRAF6)/NF-κB signaling." (PMID 36672187, 2023).
diabetic kidney disease (2 papers, 2024 to 2026). Progressive kidney disorder caused by vascular damage to the glomerular capillaries, in patients with diabetes mellitus. "MiRNA-146a and miRNA-223 are key epigenetic regulators of toll-like receptor 4 (TLR4)/tumor necrosis factor-receptor-associated factor 6 (TRAF6)/NOD-like receptor family pyrin domain-containing 3 (NLRP3) inflammasome pathway, which is involved in diabetic nephropathy (DN) pathogenesis." (PMID 39033184, 2024).
dilated cardiomyopathy (2 papers, 2014 to 2020). Cardiomyopathy which is characterized by dilation and contractile dysfunction of the left and right ventricles. "A strong association between increased Traf6 expression and pathological hypertrophy in both mice and humans was established in a 2016 experiment that noted a >2-fold increase in Traf6's expression in human dilated cardiomyopathy hearts compared to normal controls." (PMID 33102519, 2020).
endometriosis (2 papers, 2025). The growth of functional endometrial tissue in anatomic sites outside the uterine body. "miR-146a-5p, present on exosomes derived from ectopic endometrial stromal cells, facilitates M2 macrophage polarization by targeting TNF receptor-associated factor 6 (TRAF6), which subsequently supports the development of endometriosis." (PMID 40659888, 2025). "A research report published in 2024 stated that miR‐146a‐5p contained in exosomes secreted by ectopic endometrial stromal cells promotes M2 macrophage polarization through TRAF6, exacerbating the symptoms of endometriosis." (PMID 40416727, 2025).
endometritis (2 papers, 2021). An acute or chronic, usually bacterial infectious process affecting the endometrium. "We suggest that FTA alleviates LPS-induced endometritis and may be related to the targeted regulation of TRAF6 by bta-miR-2332." (PMID 33718475, 2021).
enteritis (2 papers, 2014 to 2018). Inflammation of the small intestine. "The spontaneous, microbiota-dependent enteritis that occurs in mice lacking expression of TRAF6 in CD11c+ MP could also reflect defective TGFβR-dependent signaling in mφ, as TRAF6 and its downstream partner TAK1 are critical components in this pathway." (PMID 24942685, 2014).
experimental autoimmune encephalomyelitis (2 papers, 2019 to 2022). An autoimmune demyelinating disease of the central nervous system that is produced experimentally in animals by the injection of homogenized brain or spinal cord in Freund's adjuvant. "Here we investigated the role of the CD40 downstream signaling intermediates TNF receptor‐associated factor 2 (TRAF2) and TRAF6 in MHCII+ cells in experimental autoimmune encephalomyelitis (EAE)." (PMID 30471110, 2019).
fibromyalgia (2 papers, 2025). A chronic disorder of unknown etiology characterized by pain, stiffness, and tenderness in the muscles of neck, shoulders, back, hips, arms, and legs. "Next, we observed TRAF6 expression in the mice’s DRGs: this was greater in the fibromyalgia mice (Tukey’s test, * p < 0.05, n = 6) and was inhibited by EA but not by PD-L1." (PMID 41008336, 2025). "The TRAF6 expression in the lumbar SC was increased in the fibromyalgia mice (Tukey’s test, * p < 0.05, n = 6)." (PMID 41008336, 2025). "Regarding TLR4 cascades, our results indicated comparable changes in the TLR4, MyD88, and TRAF6 protein concentrations in the fibromyalgia mice with those in the normal mice (Tukey’s test, * p < 0.05, n = 6)." (PMID 41008336, 2025). "Our findings showed that EA and PD-L1 injection can mitigate mice fibromyalgia by decreasing TLR4 and downstream molecules such as MyD88, TRAF6, and pNF-κB." (PMID 41008336, 2025).
head and neck squamous cell carcinoma (2 papers, 2018 to 2020). A squamous cell carcinoma that arises from any of the following anatomic sites: lip and oral cavity, nasal cavity, paranasal sinuses, pharynx, larynx, and salivary glands. "High TRAF6 expression leads to poor prognosis in patients with head and neck squamous cell carcinoma and promotes lymphatic metastasis." (PMID 33294443, 2020). "This study aims to investigate the role of TNF receptor‐associated factor 6 (TRAF6) on EMT and CSC regulation in squamous cell carcinoma of head and neck (SCCHN)." (PMID 29193723, 2018).
heart failure (2 papers, 2021). Inability of the heart to pump blood at an adequate rate to meet tissue metabolic requirements. "Tumor necrosis factor receptor-associated factor 6 (TRAF6), a ubiquitin E3 ligase, participates in the regulation of multiple biological processes, such as exacerbation of pathological cardiac hypertrophy, a major predisposing factor for heart failure, arrhythmia and sudden death." (PMID 34493304, 2021). "Studies in mouse models showed that has-miR-146b-5p down-regulated TRAF6 expression (known to act upstream of the NF-κB pathway) under hypoxia conditions, thereby inhibiting cardiac fibrosis and preventing cardiac dysfunction in patients with heart failure." (PMID 34781940, 2021).
hemorrhagic stroke (2 papers, 2021). A stroke caused by a bleed on the brain. "Intriguingly, TRAF6 is implicated in the manifestation of hemorrhagic stroke corresponding to its E3 ubiquitin ligase activity." (PMID 34413820, 2021). "Similarly, studies have shown that A20 reduces neuroinflammation and ameliorates brain injury by inhibiting the activity of TRAF6 E3 ubiquitin ligase after hemorrhagic stroke." (PMID 34381441, 2021).
Huntington disease (2 papers, 2013 to 2018). Huntington disease (HD) is a rare neurodegenerative disorder of the central nervous system characterized by unwanted choreatic movements, behavioral and psychiatric disturbances and dementia. "For example, the E3 ligase TRAF6 (tumor necrosis factor receptor-associated factor 6), associating with and ubiquitinating huntingtin protein, promotes huntingtin protein aggregate formation in Huntington’s disease." (PMID 30404641, 2018).
hypohidrotic ectodermal dysplasia (2 papers, 2013 to 2015). A genetic disorder of ectoderm development characterized by malformation of ectodermal structures such as skin, hair, teeth and sweat glands. "A heterozygous mutation of TRAF6 has recently been identified in a patient with hypohidrotic ectodermal dysplasia (HED)." (PMID 23758787, 2013).
IgA nephropathy (2 papers, 2022 to 2024). "BAFF is a cytokine of the tumour necrosis factor (TNF) family, and some evidence suggests it could activate the tumour necrosis receptor-associated factor 6 (TRAF6)/NF-kB pathway in glomerular mesangial cells, consequently contributing to the pathogenesis of IgA nephropathy." (PMID 35626799, 2022). "For IgA nephropathy, it is known that BAFF enhances the expression of fibroblast factors in kidneys by activating the TRAF6/NF-κB signaling pathway." (PMID 38791453, 2024). "In the case of IgA nephropathy, BAFF enhances the expression of fibroblast factors by activating the TRAF6/NF-κB signaling pathway in a rat model." (PMID 38791453, 2024).
Immunodeficiency (2 papers, 2019 to 2023). Failure of the immune system to protect the body adequately from infection, due to the absence or insufficiency of some component process or substance. "Consequentially, combined MALT1 paracaspase inactivation and TRAF6 deficiency in T cells mirrors the immunodeficiency seen upon T cell-specific MALT1 ablation." (PMID 36761777, 2023). "In fact, TRAF6 and MALT1 paracaspase double mutations yield a reciprocal rescue of both autoimmune phenotypes, resulting in an immunodeficiency as described for global or T-cell specific MALT1-deficient mice." (PMID 36761777, 2023).
latent infection (2 papers, 2017 to 2018). "As to its role in the setting of EBV latent infection, we show that LIMD1 interacts with TRAF6, a crucial mediator of LMP1 signal transduction." (PMID 29464072, 2018).
leishmaniasis (2 papers, 2014 to 2024). Infectious disease that is transmitted through the bite of hematophagous female phlebotomine sand flies. "In silico analyses demonstrated that TRAF6 is a target of miR-194 in PBMCs of dogs with leishmaniasis, and previous studies demonstrated that TRAF6 is a target of miR-194." (PMID 38241360, 2024). "Relative expression of TRAF6 was lower in PBMCs from dogs with leishmaniasis than those from healthy dogs." (PMID 38241360, 2024). "In silico analyzes demonstrated that TRAF6 is a target of miR-194 in the PBMCs of dogs with leishmaniasis." (PMID 38241360, 2024). "Basal miR-194 expression was increased in PBMC from dogs with Leishmaniasis and was negatively correlated with TRAF6 expression." (PMID 38241360, 2024). "miR-194 expression increases in peripheral blood mononuclear cells (PBMCs) of dogs with leishmaniasis with a positive correlation with the parasite load and in silico analysis demonstrated that the TRAF6 gene is the target of miR-194 in PBMCs from diseased dogs." (PMID 38241360, 2024). "To assess whether miR-194 plays a role in regulating TRAF6 expression, we analyzed the correlation between miR-194 expression and TRAF6 in PBMC from dogs with leishmaniasis." (PMID 38241360, 2024). "There is a significant negative correlation between miR-194 expression and TRAF6 expression in PBMCs from dogs with leishmaniasis." (PMID 38241360, 2024).
Lymphadenopathy (2 papers, 2013 to 2020). Enlargement (swelling) of a lymph node. "The TRAF6-ΔT mice show splenomegaly and lymphadenopathy, with a significant decrease in the percentage of CD8+ T cells but an increase in the number of CD4+ T cells." (PMID 33294443, 2020).
lymphopenia (2 papers, 2017 to 2020). Reduction in the number of lymphocytes. "Although naïve TRAF6-ΔT CD8+ T cells show normal survival when transferred into normal T cell pools, recent studies have shown that naïve TRAF6-ΔT CD8+ T cells show defective lymphopenia-induced proliferation (LIP)." (PMID 33294443, 2020).
mastitis (2 papers, 2016 to 2020). Inflammation of breast tissue during lactation or postpartum due to an obstructed duct or infection. "However, downstream signal changes revealed that NF-kB-p65, c-JNK, p38-MAPK, and TRAF6 were activated in E. coli-induced mastitis tissue samples compared with normal tissue samples." (PMID 26976286, 2016).
memory impairment (2 papers, 2019 to 2021). "MiR-146a restored learning and memory impairment in an experimental mouse model of Postoperative cognitive dysfunction (POCD) by targeting interleukin-1 receptor-associated kinase 1 (IRAK1) and TNF-receptor-associated factor 6 (TRAF6)." (PMID 31133802, 2019).
multiple sclerosis (2 papers, 2020 to 2021). A progressive autoimmune disorder affecting the central nervous system resulting in demyelination. "MiR-345-5p may act as blood biomarker in multiple sclerosis, and miR-345-3p attenuated apoptosis and inflammation caused by oxidized low-density lipoprotein by targeting TRAF6 via TAK1/p38/NF-kB signaling." (PMID 33013313, 2020).
muscle atrophy (2 papers, 2014 to 2024). The loss of muscle tissue due to inactivity or disease. "In addition, we inferred that TRAF6 exerted its function through, at least in part, the regulation of muscle-specific ubiquitin ligases (MuRF1 and MAFBx) in Dex-induced muscle atrophy." (PMID 24955790, 2014). "Inspired by these observations, we tried to determine whether MuRF1 and MAFBx could also function as the downstream signaling molecules of TRAF6 in Dex-induced muscle atrophy." (PMID 24955790, 2014).
myasthenia gravis (2 papers, 2022 to 2023). Myasthenia gravis (MG) is a rare, clinically heterogeneous, autoimmune disorder of the neuromuscular junction characterized by fatigable weakness of voluntary muscles. "This study aimed to evaluate the expression of TRAF6 in the peripheral blood B cells of myasthenia gravis (MG) patients and analyze the relationships between TRAF6 expression and clinical characteristics." (PMID 35978310, 2022). "In myasthenia gravis (MG), miR-146a is downregulated and negatively correlated with levels of messenger RNA (mRNA) such as interleukin-1 receptor-related kinase 1 (IRAK1), tumor necrosis factor (TNF) receptor-related factor 6 (TRAF6), and inducible T cell costimulator factor (ICOS)." (PMID 38058356, 2023).
myeloid leukemia (2 papers, 2023 to 2024). A clonal proliferation of myeloid cells and their precursors in the bone marrow, peripheral blood, and spleen. "Interestingly, the absence of TRAF6 in preleukemic cells has been associated with dominant myeloid leukemia and MYC-dependent stem cell characteristics." (PMID 38169510, 2024).
myocardial ischemia (2 papers, 2024 to 2025). A disorder of cardiac function caused by insufficient blood flow to the muscle tissue of the heart. "DHC was observed to alleviate myocardial ischemia/reperfusion damage by suppressing apoptosis, inflammation, and oxidative stress through the inhibition of the TNF receptor-associated factor 6 (TRAF6)/NF-κB signaling pathway." (PMID 39202856, 2024).
NK/T cell lymphoma (2 papers, 2014). "Recently, Jin Ho Paik, et.al 2011, also reported that miR-146a may function as a tumor-suppressor in NK/T cell lymphoma by down regulating the NF-κB through targeting TRAF6." (PMID 25083878, 2014).